NAT10 (N-acetyltransferase 10)
Diseases named in the same sentence as NAT10 in open-access papers (continued):
Sharing a sentence is not in itself a finding about the gene and the disease.
gastric cancer (continued). "Human N-acetyltransferase 10 (NAT10) is one of the targets of miR-330-3p, which is highly expressed and may be a pro-oncogene in several tumors, including hepatocellular carcinoma and gastric cancer." (PMID 36568518, 2022). "Taken together, we speculated that the upregulation of DARS-AS1 weakened the viabilities and invasion of gastric cancer cells by sponging miR-330-3p to regulate NAT10 expression." (PMID 36568518, 2022). "We speculated that DARS-AS1 may act as a ceRNA by sponging miR-330-3p to regulate NAT10 expression during gastric cancer progression." (PMID 36568518, 2022). "Bioinformatics prediction and dual-luciferase reporter assay results show that DARS-AS1 may sponge miR-330-3p and then modulate NAT10 in gastric cancer cells." (PMID 36568518, 2022). "We further investigated whether miR-330-3p/NAT10 signaling contributed to DARS-AS1-induced gastric cancer cell proliferation, migration, and invasion." (PMID 36568518, 2022). "A previous study revealed that in gastric cancer (GC), NAT10 directly interacts with the 3'UTR of COL5A1 mRNA to regulate its ac4C modification, thereby promoting GC metastasis and EMT." (PMID 41316475, 2025). "Here, we unveil a previously unrecognized NAT10/XIST/YAP1/VEGFA signaling axis driving vascular abnormalization in gastric cancer (GC) and demonstrate its therapeutic potential in remodeling the tumor immune microenvironment." (PMID 40860183, 2025). "ac4C mRNA modification status and NAT10 expression levels were analyzed in gastric cancer (GC) samples and compared with the corresponding normal tissues." (PMID 36609449, 2023). "Gastric cancer (GC) showed elevated levels of ac4C mRNA modification as well as its acetyltransferase NAT10, which correlated with disease progression and poor patient prognosis." (PMID 37612540, 2023). "In addition, the silencing of DARS-AS1 and NAT10 could suppress cell behaviors by directly adjusting miR-330-3p in gastric cancer." (PMID 36568518, 2022). "Importantly, the DARS-AS1/miR-330-3p/NAT10 axis may help to develop novel prognosis biomarkers and treatment strategies, which may provide a new hint for comprehending the mechanism of gastric cancer progression." (PMID 36568518, 2022). "Molecular mechanism studies show that NAT10 directly binds to the 3′ UTR region of COL5A1 mRNA in an ac4C modification‐dependent manner, promoting COL5A1 expression and thus promoting gastric cancer cell metastasis and EMT137." (PMID 39764566, 2025). "NAT10 was reported to regulate glucose metabolism reprogramming through regulating SEPT9, which in turn regulates HIF-1 pathway activation in gastric cancer." (PMID 40588654, 2025). "NAT10-mediated ac4C of COL5A1 promotes metastasis and EMT in gastric cancer, and NAT10-mediated ac4C acetylation of mRNA promotes the development of bladder cancer." (PMID 40169553, 2025). "Previous studies have reported that N4-acetylcytidine drives glycolysis in gastric cancer via a NAT10/SEPT9/HIF-1α positive feedback loop, and the lncRNA CCAT1 facilitates the progression of gastric cancer via PTBP1-mediated enhancement of glycolysis." (PMID 40796546, 2025). "Further research found that high NAT10 expression promotes the expression of IM and MMP2 through RNA acetylation modification, ultimately promoting EMT in gastric cancer." (PMID 39764566, 2025). "In gastric cancer, the lncRNA DARS-AS1 acts as a ceRNA by binding to miR-330-3p, which in turn regulates NAT10 expression and promotes cancer progression." (PMID 40881352, 2025). "For example, under hypoxic microenvironments, HIF-1α acts on NAT10 HRE sequences, activating its expression and promoting glucose metabolic reprogramming in gastric cancer cells." (PMID 41298345, 2025). "Collectively, these results suggest that NAT10 promotes VEGFA expression and angiogenesis in gastric cancer by acetylating the lncRNA XIST." (PMID 40860183, 2025).
gastric cancer (continued). "Bioinformatics analysis of the GEO data using the Kaplan–Meier Plotter further demonstrated that high expression of NAT10 was correlated with shorter overall survival, first progression (FP) and post progression survival (PPS) in gastric cancer patients." (PMID 36609449, 2023). "This study aimed to investigate the influence of DARS-AS1 on gastric cancer progression and explore the potential regulatory network of DARS-AS1/miR-330-3p/NAT10." (PMID 36568518, 2022). "In gastric cancer, NAT10 was reported to control COL5A1 via NAT10 mediated ac4C pathway, which implicates in EMT and metastasis processes." (PMID 36149760, 2022). "Furthermore, N-acetyltransferase 10 (NAT10) interacts with YTHDF1 pre-mRNA, thereby inducing elevated skipping of YTHDF1 exon 4 that can stimulate gastric cancer cell proliferation." (PMID 40986143, 2025). "Moreover, a recent study revealed previously uncharacterized biological functions of NAT10, demonstrating that NAT10 regulates m6A‐modified target genes via liquid–liquid phase separation (LLPS), thereby promoting gastric cancer progression." (PMID 39764566, 2025). "Taken together, targeting the NAT10/XIST/YAP1 axis-mediated vascular abnormalization by using Remodelin and Verteporfin could enhance immune checkpoint blockade in gastric cancer." (PMID 40860183, 2025). "N-acetyltransferase 10 (NAT10), the sole identified ac4C acetyltransferase, is considered to be vital in various cellular biological processes, including periodontal stem cell osteogenic differentiation, gastric cancer cell metastasis, and multiple myeloma cell apoptosis." (PMID 40362562, 2025). "In summary, our study uncovered that NAT10-mediated ac4C modification stabilizes lncRNA XIST, which recruits hnRNPK to facilitate YAP1 nuclear translocation and transcriptional activation, thereby driving VEGFA-dependent vascular abnormalization in gastric cancer." (PMID 40860183, 2025). "The C‐terminal intrinsically disrupt the region of NAT10 to alter the liquid–liquid phase separation (LLPS) and regulate m6A reader YTH N6‐methyladenosine RNA binding protein 1 (YTHDF1) splicing thereby promoting gastric cancer (GC) progression." (PMID 39640362, 2024).
bladder cancer (37 papers, 2018 to 2025). "NAT10‐mediated ac4C modification has also been reported to be associated with cisplatin chemoresistance in bladder cancer." (PMID 39817252, 2025). "In bladder cancer, NAT10 overexpression has been linked to chemotherapy resistance, as well as poor prognosis and clinical outcomes." (PMID 41316475, 2025). "Deficient NAT10 in both xenograft and transgenic mouse models of bladder cancer reduced the tumor burden." (PMID 35522942, 2022). "Tumour grading statistics in both the control and the NAT10‐cKO groups indicated that the loss of Nat10 in bladder cancer stem cells effectively delayed cancer progression." (PMID 35522942, 2022). "NAT10 significantly improves tumor progression by controlling mRNA stability and translation and is linked to poor prognosis in multiple cancer types, including colorectal and bladder cancer." (PMID 41310903, 2025). "NAT10, the only known acetyltransferase mediating N4-acetylcytidine (ac4C) modification in eukaryotes, has been implicated in promoting tumorigenesis and progression in colon cancer, bladder cancer, pancreatic ductal cancer, among others." (PMID 41408025, 2025). "Previous studies have demonstrated that NAT10 promotes cisplatin resistance in bladder cancer by indirectly facilitating DNA damage response (DDR) through post-transcriptional regulation of AHNAK mRNA stability." (PMID 40908816, 2025). "In bladder cancer, cisplatin activates NF-κB signaling, which increases NAT10 transcription, resulting in enhanced mRNA stability through ac4C modification and improved DNA damage repair, thus promoting chemoresistance." (PMID 40881352, 2025). "This interaction bolstered cisplatin chemoresistance in bladder cancer cells by augmenting DNA damage repair mechanisms, underscoring the pivotal role of NAT10 in mediating therapeutic resistance via modulation of cellular repair pathways." (PMID 40588654, 2025). "NAT10 confers resistance to cisplatin chemotherapy in bladder cancer cells by enhancing DNA damage repair (DDR), which is regulated by AHNAK." (PMID 41316475, 2025). "Earlier studies using xenograft and mouse-based models of transgenic bladder cancer revealed that both NAT10 downregulation and its absence can lead to a reduction in tumor burden." (PMID 41316475, 2025). "Nuclear factor kappa B (NF-κB) is implicated as a positive regulator to induce the expression of NAT10 in bladder cancer." (PMID 40288646, 2025). "In bladder cancer, NAT10 knockdown specifically attenuated mRNA ac4C modification, impairing translation efficiency of BCL9L/SOX4/AKT1 and accelerating degradation of BCL9L/SOX4 transcripts." (PMID 40881352, 2025). "Chloride intracellular channel 3 (CLIC3) interacts with NAT10 and inhibits its function to promote bladder cancer progression, resulting in the downregulation of ac4C modification and the stability of p21 mRNA." (PMID 41316475, 2025). "Studies have found that NAT10 promotes cisplatin resistance in bladder cancer by enhancing AHNAK-mediated DNA damage repair." (PMID 39742262, 2024). "Consistent with the previous study, we verified that NAT10 knockdown inhibited the viability of bladder cancer cells UMUC3 and T24." (PMID 38182571, 2024). "Previous study found that NAT10 drove the cisplatin resistance by promoting the mRNA stability of AHNAK in bladder cancer." (PMID 39085201, 2024). "CLIC3 interacts with NAT10 to inhibit NAT10‐mediated ac4C modification of p21 mRNA, thereby promoting bladder cancer progression." (PMID 39640362, 2024). "NAT10‐mediated ac4C acetylation of AHNAK promotes cisplatin resistance in bladder cancer by activating the AHNAK‐mediated DNA damage repair pathway." (PMID 39640362, 2024). "Recent studies have shown that the onset and progression of various cancers, including bladder cancer (BCa), breast cancer (BC), cervical cancer (CC), colorectal cancer (CRC), and so on, are associated with NAT10‐catalyzed ac4C modification." (PMID 39640362, 2024).
bladder cancer (continued). "Regulation of ac4C via NAT10 involves proliferation, migration, and stem cell properties of bladder cancer cells." (PMID 39006762, 2024). "NAT10 plays a pivotal role in bladder cancer cell lines by influencing proliferation, metastasis, and cisplatin chemoresistance." (PMID 39156764, 2024). "These authors suggested NAT10 as a therapeutic target to overcome cisplatin resistance in bladder cancers." (PMID 37322549, 2023). "In this study, we established conditional knockout mice to ablate Nat10 in K14+ bladder cancer stem cells to investigate the function and regulatory networks of the acetyltransferase NAT10 in vivo." (PMID 35522942, 2022). "The downregulation of NAT10 was shown to result in the reduced ac4C modification of mRNA in specific regions of bladder cancer cells, impairing the translational stability and efficiency of BCL9L, SOX4, and AKT1." (PMID 36360287, 2022). "In summary, these findings provide new insights into the dynamic characteristics of mRNA's post‐transcriptional modification via NAT10‐dependent acetylation and predict a role for NAT10 as a therapeutic target in bladder cancer." (PMID 35522942, 2022). "The deletion of NAT10 was also shown to reduce tumor burden in bladder cancer xenograft and transgenic mouse models." (PMID 36360287, 2022). "Consistent with the results from BLCA patients, NAT10 showed a higher level of expression in BBN‐induced mouse bladder cancer than in corresponding normal tissues." (PMID 35522942, 2022). "To summarise, the dynamic accommodation of BCL9L, SOX4 and AKT1 transcripts mediated by NAT10‐dependent ac4C modification is critical for the progression of bladder cancer." (PMID 35522942, 2022). "NAT10 was essential for the proliferation, migration, invasion, survival and the stem‐cell‐like properties of bladder cancer cell lines." (PMID 35522942, 2022). "Bladder cancer in wild‐type and NAT10‐cKO mice was induced by continuously supplementing their drinking water with BBN for 16 weeks." (PMID 35522942, 2022). "Similarly, previous studies in prostate and bladder cancer discover that NAT10-mediated ac4C modification promotes the tumor growth of xenografted mice." (PMID 40245789, 2025). "Therefore, NAT10 is believed to regulate the expression of these target genes by ac4C modification, thus promoting bladder cancer progression." (PMID 39817252, 2025). "To investigate whether the effects of CLIC3 on ac4C modification of p21 mRNA were mediated via NAT10, we constructed a stable model of CLIC3 over-expressed in NAT10-knockdown bladder cancer cells." (PMID 38182571, 2024). "However, we also observed that knockdown of NAT10 promoted the proliferation of bladder cancer cells J82 and TCCSUP." (PMID 38182571, 2024). "Remodelin, by inhibiting NAT10 expression, has been found to increase bladder cancer patients’ sensitivity to cisplatin, reducing the S phase population in the cell cycle, enhancing bladder cancer cell chemosensitivity to cisplatin, and inducing apoptosis." (PMID 39033778, 2024). "In addition, NAT10 contributes to bladder cancer progression by mediating N4-acetylcytidine modification of mRNA." (PMID 38243170, 2024). "High expression of NAT10 is necessary for the tumorigenic properties of bladder cancer." (PMID 39006762, 2024). "In general, CLIC3 could interact with NAT10 in the nucleus, where it inhibited NAT10-mediated ac4C modification of p21 mRNA, and promote cell growth in bladder cancer." (PMID 38182571, 2024). "However, previous studies report that NAT10 knockdown inhibits the viability of bladder cancer cells T24 and UMUC3." (PMID 38182571, 2024). "In this section, we utilised an animal model that is more analogous to human bladder cancer to ultimately substantiate the role of NAT10 in regulating the expression of targets such as BCL9L, SOX4 and AKT1 through ac4C modification, therefore, promoting BLCA progression." (PMID 35522942, 2022).
bladder cancer (continued). "Also in bladder cancer, ac4C modification mediated by NAT-10 has been certified to increase bladder cancer progression." (PMID 36545327, 2022). "Furthermore, acetylated RNA immunoprecipitation sequencing data and RNA immunoprecipitation qPCR results revealed that NAT10 is responsible for a set of ac4C mRNA modifications in bladder cancer cells." (PMID 35522942, 2022). "Furthermore, CLIC3 and NAT10 were colocalized in the nuclear of bladder cancer cells." (PMID 38182571, 2024). "Moreover, ac4C-RIP assays indicated that p21 mRNA could undergo ac4C modification, and NAT10 knockdown decreased the ac4C modification of p21 mRNA in bladder cancer cells." (PMID 38182571, 2024). "Moreover, knockdown of NAT10 promoted the proliferation of bladder cancer cells J82 and TCCSUP." (PMID 38182571, 2024). "However, the role of NAT10‐mediated acetylation modification in bladder cancer remains elusive." (PMID 35522942, 2022). "NAT10 can stimulate DNA damage repair by binding to and stabilizing AHNAK mRNA, thereby promoting bladder cancer cisplatin chemoresistance." (PMID 39817252, 2025). "NAT10 mediates ac4C modification of oncogenes (BCL9L, SOX4, and AKT1) in bladder cancer to enhance their mRNA stability, thereby promoting cancer cell malignant behaviors and stem-cell-like properties." (PMID 40999468, 2025). "For example, NAT10 acetylates CEP170 mRNA to enhance CEP170 translation efficiency and leads to myeloma growth, and NAT10 promotes cisplatin chemoresistance in bladder cancer cells by enhancing DNA damage repair (DDR)." (PMID 39246323, 2024). "Similarly, NAT10 stabilizes BCL9L, SOX4, and AKT1 transcripts in bladder cancer through 3'UTR ac4C modification, fueling proliferation and invasion." (PMID 40588654, 2025). "N-acetyltransferase 10 (NAT10) is a protein that acts as an acetyltransferase, has distinct catalytic and regulatory functions, and is involved in the progression of various cancers such as bladder cancer, hepatocellular carcinoma, and multiple myeloma." (PMID 41189569, 2025). "NAT10 mediates ac4C acetylation of BCL9L, SOX4, and AKT1, enhancing their mRNA stability and promoting proliferation, migration, and stemness while inhibiting apoptosis in bladder cancer." (PMID 39640362, 2024). "The down-regulation of NAT10 results in the reduction of ac4C modification in specific regions of mRNA, impairing translational efficiency of BCL9L, SOX4, AKT1 as well as the stability of BCL9R and SOX5, thereby reducing bladder cancer burden." (PMID 38233839, 2024). "Collectively, we proposed a TFCR-based framework to screen for key genes in bladder cancer, and revealed that CLIC3 could be a regulatory factor of NAT10-catalyzed ac4C modification, elucidating a novel mechanism for mRNA ac4C modification." (PMID 38182571, 2024). "To explore whether this elevated expression level of NAT10 has biological significance in the development of bladder cancer, we treated BBN‐induced BLCA mice with the NAT10‐specific inhibitor Remodelin for 4 weeks." (PMID 35522942, 2022). "However, we demonstrated that CLIC3, mainly located in the nucleus, could interact with NAT10, but not with Rab25, to promote cell proliferation in bladder cancer." (PMID 38182571, 2024).